CCR8 (C-C motif chemokine receptor 8)
Diseases named in the same sentence as CCR8 in open-access papers (continued):
Sharing a sentence is not in itself a finding about the gene and the disease.
gastric cancer (6 papers, 2020 to 2025). A primary or metastatic malignant neoplasm involving the stomach. "Future research on anti-CCR8 antibody therapy targeting CCR8+ Tregs in gastric cancer is highly anticipated." (PMID 41323783, 2025). "Our research showed that CCR8+ Tregs localize to the tumor invasion boundary in gastric cancer and can suppress the proliferation and GzmB expression of closely infiltrating CD8+ T cells." (PMID 41323783, 2025). "We examined continuous tissue sections from 80 gastric cancer patients using dual staining for CCR8/Foxp3 and GzmB/CD8." (PMID 41323783, 2025). "This is the first report to show, using spatial analysis, that CCR8+ Tregs suppress nearby CD8+ T cells in gastric cancer." (PMID 41323783, 2025). "In gastric cancer, tumor-infiltrated Tregs with higher expression of CCR8 produce more IL-10 molecules in vitro." (PMID 40186298, 2025). "In a gastric cancer mouse model, CCR8 blockade downregulated Treg-produced IL-10 and reversed the suppression by Tregs on the secretion and proliferation of CD8+ T cells." (PMID 40186298, 2025). "Based on the immunofluorescence staining results, 54 CRC patients and 60 gastric cancer (GC) patients were divided into the following two groups: a high TNFR2+CCR8+ Treg infiltration group and a low TNFR2+CCR8+ Treg infiltration group." (PMID 37935468, 2024). "The presence of tumor-specific activated stromal cells in our data suggest the applicability of cell type depletion strategies that are currently under development such as LRRC15 and CCR8 antibody drug conjugates in gastric cancer." (PMID 36550535, 2022). "Our current results from the immunohistological analysis of human gastric cancer tissues suggest that CCR8+ Tregs may inhibit the proliferation and GzmB expression of surrounding CD8+ T cells, leading to the suppression of antitumor immunity." (PMID 41323783, 2025). "Targeting CCR8+ Tregs may offer a promising strategy to improve the efficacy of immunotherapy in gastric cancer." (PMID 41323783, 2025). "Therefore, anti-CCR8 antibodies might enhance antitumor immunity in gastric cancer tumors where CCR8+ Tregs actively suppress immune responses." (PMID 41323783, 2025). "However, the role of CCR8+ Tregs in gastric cancer remains unclear." (PMID 41323783, 2025). "In this study, we analyzed the infiltration of CCR8+ Tregs and GzmB+ CD8+ T cells in gastric cancer tissues using IHC dual staining and evaluated their association with tumor stage, prognosis, and spatial distribution." (PMID 41323783, 2025). "This study analyzed the infiltration and distribution of CCR8+ Tregs and CD8+ T cells in gastric cancer tissues and evaluated their impact on CD8+ T cells and patient prognosis." (PMID 41323783, 2025). "However, the role of IL-7 and CCR8 in gastric cancer development has not yet been clarified." (PMID 33816214, 2020). "Finally, we identified that TNFR2+CCR8+ Tregs but not total Tregs were positively correlated with adverse prognosis in patients with CRC and gastric cancer." (PMID 37935468, 2024).
non-small cell lung carcinoma (6 papers, 2022 to 2025). A group of at least three distinct histological types of lung cancer, including non-small cell squamous cell carcinoma, adenocarcinoma, and large cell carcinoma. "In order to determine if CCR8+ FOXP3− Tconv cells are enriched in human tumors, we analyzed CD4+ T cells from 48 patents with non-small cell lung carcinoma (NSCLC) by flow cytometry." (PMID 38100544, 2023).
atopic dermatitis (5 papers, 2004 to 2023). "In mice, CCR8 has been associated with the recruitment of Th2 cells to sites of atopic dermatitis, and CCR8 transcripts are induced in cutaneous Trm cells following the resolution of viral infections." (PMID 29427415, 2018). "The role of CCR4, CCR8, CCR10, and CCR6 or their ligands has been proposed in atopic dermatitis (AD), psoriasis, cutaneous lupus erythematosus, systemic sclerosis, or malignant skin tumors, but not in CU." (PMID 37371632, 2023). "Chemokine receptors such as chemokine (C-C motif) receptor 4 (CCR4) or CCR8 have been studied in skin diseases, e.g., atopic dermatitis, but not in CU." (PMID 37371632, 2023). "Analysis by immunohistochemistry of airway mucosa of people with atopic asthma after antigen challenge revealed that large numbers of CCR4+ and CCR8+ T cells express IL-4, and CCR4 expression was prominent in people with severe atopic dermatitis, which decreased upon abatement of disease activity." (PMID 15526056, 2004).
bladder cancer (5 papers, 2020 to 2025). "Previous studies have shown that CCR8 plays a role in the immunosuppressive function of Tregs, and antagonism of CCR8 has been reported to inhibit tumor growth in a few cancer types, including triple-negative breast cancer and bladder cancer." (PMID 40186298, 2025). "We previously demonstrated that monocytic and granulocytic myeloid cells obtained from peripheral blood and in tumor-infiltrating leukocytes of patients with bladder cancer display an increased expression of CCR8." (PMID 31811337, 2020). "Remarkably, CCR8 expression detected in bladder cancer tissue and was limited to the tumor-infiltrating myeloid cells, including TAMs." (PMID 31811337, 2020). "There are studies showed CCL18 may enhance migration and invasion by binding CCR8 in bladder cancer cells." (PMID 34893045, 2021). "Given the increased levels of CCR8-expressing cells in patients with bladder cancer, CCR8 and/or CCR8-related ligands could represent an attractive target for therapy of bladder cancer." (PMID 31811337, 2020).
allergic disease (4 papers, 2010 to 2025). An immune response that occurs following re-exposure to an innocuous antigen, and that requires the presence of existing antibodies against that antigen. "We had also explored whether there was any association of CCR8 expression with serum markers of allergy (IgE and eosinophils) in both asthmatics and normal controls." (PMID 20455898, 2010). "In particular, we demonstrated that Ephedra Herb is a potential medical agent for TH2-mediated allergic diseases by inhibiting the cell migration mediated by the TH2-relevant chemokine receptors such as CCR3, CCR4, and CCR8." (PMID 27376063, 2016). "As TH2 cells selectively express CCR3, CCR4, and CCR8, these data suggest that Ephedra Herb has a potency to strongly suppress cell migration of TH2 cells and TH2 cell-mediated allergic reactions." (PMID 27376063, 2016). "Another study on bile duct sclerosis suggested that IgG-associated CCL1 chemotaxis of Th2 and Foxp3+ Treg cells occurs via the CCL1/CCR8 pathway, although these studies did not focus on airways and allergies." (PMID 40051629, 2025).
Hepatic fibrosis (4 papers, 2012 to 2024). The presence of excessive fibrous connective tissue in the liver. "Additionally, use of CCR1-, CCR2-, CCR5-, and CCR8-deficient mice or pharmacological inhibition of these axes reduced hepatic macrophage infiltration, hepatic fibrosis, and hepatocellular damage in experimental models of chronic liver injury." (PMID 31921154, 2019). "CCR8-deficient mice showed significantly reduced hepatic fibrosis in two independent experimental models, which was accompanied by reduced intrahepatic monocytes/macrophages and could be restored by adoptively transferring CCR8-expressing Ly6Chi bone marrow monocytes." (PMID 23259611, 2012). "In the progress of liver fibrosis, peripheral pro-inflammatory mononuclear MoMφs can be attracted to the liver depending on CCL2/CCR2, CCL5/CCR5, and CCL1/CCR8 chemokines axis and aggravate liver fibrosis." (PMID 39635524, 2024). "Hence, the inhibition of CCL2/CCR2, CCL5/CCR5, and CCL1/CCR8 chemotaxis shows potential efficacy to repair liver fibrosis." (PMID 39635524, 2024). "In the respective study, CCR8-deficient mice having reduced intrahepatic monocytes/macrophages showed significantly attenuated hepatic fibrosis that could be restored by adoptive transfer of CCR8-expressing Ly-6Chigh BM-derived monocytes." (PMID 31849997, 2019).
lymphoma (4 papers, 2016 to 2025). A malignant (clonal) proliferation of B- lymphocytes or T- lymphocytes which involves the lymph nodes, bone marrow and/or extranodal sites. "Recently some studies focusing on the behavior of CCR8 in carcinogenesis were conducted and have implicated an anti-apoptosis effect of CCR8 in lymphoma and T cell leukemia through an autocrine manner." (PMID 26716905, 2016). "Although CCR3, CCR6, CCR8, PITPNM3, and GPER1 encode receptors of CCL18, only CCR6 was expressed in the lymphoma cells." (PMID 39894788, 2025). "Our immunohistochemical analysis demonstrated moderate to strong expression of CCR5, CCR6, and CCR8 on the surface of the lymphoma cells in all of the investigated subgroups." (PMID 35887224, 2022). "Interestingly, the percentage of the lymphoma cells stained positively for CCR5 and CCR8 was lower in the RS samples compared with GCB-, NGCB-DLBCL, and tFL (90% CCR5+ cells in GCB- and NGCB-DLBCL and 83.3% for tFL vs. 70% for RS, p < 0.1) confirming the RNA data." (PMID 35887224, 2022).
renal carcinoma (4 papers, 2014 to 2025). A carcinoma arising from the epithelium of the renal parenchyma or the renal pelvis. "Recent evidences revealed the chemotaxis of CCR8+ human malignant tumor cells towards lymph node, and a significantly increased CCR8 expression in renal carcinomas patients." (PMID 26716905, 2016). "Together, these findings confirmed the relationship of PTP4A3 to immune cell infiltration and CD79A, CSF1R, INOS, COX2, STAT5A, FOXP3 and CCR8 in KIRP, suggesting an important immune regulation role of PTP4A3 in the renal cancer microenvironment." (PMID 34630392, 2021). "In addition to recruiting Tregs, a group of CD11b(+)CCR8(+) myeloid cells similar to MDSCs recruited by CCR8/CCL1 interaction in urothelial and renal carcinomas also “educate” tumor infiltrating T cells to express FoxP3, a marker for Tregs." (PMID 25110692, 2014).
colorectal tumors (3 papers, 2021 to 2025). "We have recently reported using 225Actinium-labeled anti-CCR8 IgG for killing CCR8+ ti-Tregs in murine colorectal tumors which synergized with subsequent anti-CTLA4 ICI." (PMID 41302499, 2025). "Targeting of CCR8 can effectively reduce the resident Treg of colorectal tumors." (PMID 34884642, 2021). "CT26 and MC38 murine colorectal tumors were initiated in female Balb/c and C57Bl6 mice, respectively, and when the tumors reached a volume of ~200 mm3, the mice were randomized into the groups of four animals, and injected into the tail vein with either 200 μCi anti-CCR8 111In-IgG or 111In-Fab." (PMID 41302499, 2025). "We established the presence of CD45+CD4+CD25+CCR8+ ti-Tregs in MC38 and CT26 colorectal tumor models that constituted more than 40% of all tumors infiltrating Tregs." (PMID 41035646, 2025).
hepatocellular carcinoma (3 papers, 2025). A malignant tumor that arises from hepatocytes. "Recently, CCR8 has been identified as a key chemokine receptor expressed on tumor-infiltrating Tregs and targeted blockade of CCR8 exerts anticancer effect in several cancer types, but whether this pathway is involved in the progression of hepatocellular carcinoma (HCC) remains unclear." (PMID 40186298, 2025). "For instance, Tregs, which abundantly express CCR4, CCR8 and CCR10, were directed to hepatocellular carcinoma (HCC) sites, where their corresponding ligands, CCL22 and CCL28, were present, affecting the treatment outcome by evading the immune system." (PMID 40852716, 2025).
liver cancer (3 papers, 2021 to 2025). An epithelial or non-epithelial malignant neoplasm that arises from the liver. "In the present study, we attempted to determine the potential involvement of CCR8+ Tregs in human HCC tissues and to examine the anticancer effect and the underlying molecular mechanisms of the CCR8 antagonistic antibody, IPG0521m, in murine liver cancer model." (PMID 40186298, 2025). "CCR8 antagonism robustly suppressed liver cancer growth via switching the highly immunosuppressive TI-Tregs to less an immunosuppressive phenotype, leading to elevated anticancer immunity and a long-lasting tumor-suppressing effect." (PMID 40186298, 2025). "To examine whether CCR8 blockade suppresses liver cancer growth, we generated a monoclonal CCR8 antibody named IPG0521, which bound CCR8 originated from human, monkey, dog, rat, and mouse with high affinity, and potently inhibited CCR8-mediated chemotaxis and intracellular signaling." (PMID 40186298, 2025). "In the following study involving a murine liver cancer model, IPG0521 with murine IgG2a Fc was constructed, named IPG0521m, which potently blocked the chemotaxis of CCR8+ Treg derived from murine cancer models." (PMID 40186298, 2025).
lymph node metastasis (3 papers, 2015 to 2024). "When comparing clinicopathological characteristics, the low GzmB/CCR8 ratio group from the ROI protocol had significantly higher rates of lymph node metastasis (34.1% vs. 12.5%, respectively, P = 0.035) and pleural invasion (22.0% vs. 5.0%, respectively, P = 0.048)." (PMID 38783281, 2024). "Meanwhile, in the 89 patients with lymph node metastasis, 53 patients co-expressed CCR7 and MUC1 (59.6 %), seven patients only expressed CCR7 (13.2 %), 18 patients only expressed MUC1 (20.2 %), and 11 patients did not express CCR8 or MUC1 (12.4 %)." (PMID 26667143, 2015).
oral cancer (3 papers, 2020 to 2024). "The expression of CCR4, CXCR3, CCR2, and CCR8 was higher in highly invasive oral cancer cell lines (SCC-25, CAL-27, and FaDu) than in the less aggressive cell line (HSC-2), whereas CCL19 and P2RY14 expression showed the opposite trend." (PMID 38213736, 2024). "Our results were consistent with previous data in other malignancies, showing an imbalance between Th2/Th1 subsets in cancer with more than half of the Tregs found in oral cancer being either Th2-like or CCR8+ Tregs." (PMID 34025655, 2021). "Specifically, these findings indicate that CCR4, CXCR3, CCR2, and CCR8 may affect the invasiveness of oral cancer cells." (PMID 38213736, 2024). "Overall, our data suggest that the secretome from oral cancer induces CCR8 and promotes a Th2 lineage in the T cell repertoire by several mechanisms; rapid membrane VitD mediated PGE2 production, accumulation of Vitamin D in cancer areas and increasing CCL18 levels." (PMID 34025655, 2021). "CCL1 and CCL18 may either play a role in CCR8+ Treg migration to the malignant zone of oral cancer or they might induce its expression directly, thus, we measure chemotaxis and CCR8 induction in response to recombinant chemokines CCL1 and CCL18." (PMID 34025655, 2021). "In this study, we also determined the expression levels of CCR6 and CCR8 in oral cancer." (PMID 32641093, 2020). "We further examined the expression of CCR4, CXCR3, P2RY14, CCR2, CCR8, and CCL19 in highly aggressive oral cancer cell lines and tissues." (PMID 38213736, 2024). "Further analysis of gene expression in clinical tissues revealed that CCR4, CXCR3, CCR2, and CCR8 exhibited higher expression in oral cancer cells of patients with metastasis compared to those without, whereas CCL19 and P2RY14 displayed the opposite trend." (PMID 38213736, 2024).
pulmonary fibrosis (3 papers, 2024 to 2025). Chronic progressive interstitial lung disorder characterized by the replacement of the lung tissue by connective tissue, leading to progressive dyspnea, respiratory failure, or right heart failure. "Targeting CCR8 could represent a novel therapeutic strategy for pulmonary fibrosis." (PMID 39768150, 2024). "Experiments in mice showed that blocking C-C chemokine receptor 8 (CCR8) prevented TRM cell recruitment and inhibited lung fibrosis." (PMID 40433386, 2025). "Although other chemokine-receptor pairs, such as CCL1, CCL8, and CCR8, garnered our attention, these findings suggest the intriguing possibility that the CXCR6-CXCL16 axis may play a role in specific immune cell recruitment and contribute to the pathogenesis of pulmonary fibrosis." (PMID 38789926, 2024).
airway hyperresponsiveness (2 papers, 2008 to 2011). "Airway eosinophilia and airway hyperresponsiveness (AHR), however, are not diminished in CCR8-/- mice and adoptively transferred Th2 cells not expressing CCR8 accumulate in the lungs." (PMID 21867534, 2011).
Breast Invasive Carcinoma (2 papers, 2023 to 2024). "Our findings suggest that CCR8-targeted therapies could enhance cancer immunotherapy outcomes, with breast invasive carcinoma (BRCA) emerging as a promising indication for combination therapy." (PMID 39273290, 2024). "Our findings revealed strong correlations between CCR8 and specific cancers, notably Breast Invasive Carcinoma (BRCA), Colon Adenocarcinoma (COAD), Head and Neck Squamous Cell Carcinoma (HNSC), Rectum adenocarcinoma (READ), Stomach adenocarcinoma (STAD), and Thyroid carcinoma (THCA)." (PMID 38001911, 2023). "The correlation of CCR8 with immune checkpoint proteins and genomic instability markers such as TMB and MSI further supports its potential in combination therapies for various cancer types, particularly breast invasive carcinoma (BRCA)." (PMID 39273290, 2024).
colorectal adenocarcinoma (2 papers, 2021). The most common type of colorectal carcinoma. "Using Ccr8‐deficient mice to confirm the specificity of anti‐CCR8 staining, our findings validate prior conclusions that Treg cells infiltrating MC38 colorectal adenocarcinoma tumours express high levels of CCR8 on their cell surface." (PMID 33838058, 2021). "To examine the expression of CCR8 on tumour‐infiltrating T cells, we subcutaneously implanted syngeneic MC38 colorectal adenocarcinoma cells into wild‐type (WT) C57BL/6 animals." (PMID 33838058, 2021). "Collectively, these findings suggest that CCR8 function does not substantially affect anti‐tumour immune responses in the syngeneic MC38 colorectal adenocarcinoma model, despite its sensitivity to Treg cell ablation." (PMID 33838058, 2021).
eosinophilia (2 papers, 2011 to 2020). "CCL8 induced eosinophilia through recruiting IL-5-producing CCR8+Th2 cell in AD murine model." (PMID 32280674, 2020).
glioma (2 papers, 2022 to 2023). A benign or malignant brain and spinal cord tumor that arises from glial cells (astrocytes, oligodendrocytes, ependymal cells). "The Spearman correlation analysis results suggested that the immune marker sets of Treg (FOXP3, CCR8, TGFβ1), TAM (CCL2, CD68, IL-10), and MDSC (CD33, ITGAM, FUT4) were significantly associated with the PROS1 expression in glioma." (PMID 36685506, 2022). "RT-qPCR, western blot, flow cytometry, immunofluorescence, luciferase reporter assay, chromatin immunoprecipitation and ELISA were performed to measure the effect of lactate on the regulation of CD39, CD73 and CCR8 in cultured glioma stem cells, CD4 + T cells or macrophages." (PMID 37770937, 2023). "Lactate accumulation within cells upregulated CD39, CD73 and CCR8 expressions in both lactate-treated cells and glioma stem cells-co-cultured CD4 + T cells and macrophages, and intracellular lactate directly elevated the activities of these gene promotors through histone H3K18 lactylation." (PMID 37770937, 2023).
graft versus host disease (2 papers, 2021). An immune system disorder that occurs after allogeneic hematopoietic stem cell transplant and is a reaction of donor immune cells against host tissues. "The role of CCR8 in Tregs physiopathology was initially demonstrated in the field of transplantation where Ccr8-deficient Tregs were unable to prevent T cell-induced graft-versus-host disease in lung and colon tissues." (PMID 33924428, 2021).